BCAT1 (branched chain amino acid transaminase 1)
Diseases named in the same sentence as BCAT1 in open-access papers (continued):
Sharing a sentence is not in itself a finding about the gene and the disease.
Hypertension (2 papers, 2018 to 2024). The presence of chronic increased pressure in the systemic arterial system. "Only one researcher found that BCAT1 was co-expressed in hypertension and renal cell carcinoma by bioinformatic analysis and may be a key gene in hypertension-associated renal cell carcinoma." (PMID 39324007, 2024).
liver disease (2 papers, 2018 to 2024). "Next, we evaluated the correlation between BCAT1 expression and other markers of advanced liver disease." (PMID 30265706, 2018).
lung disease (2 papers, 2020 to 2022). "Overall, our results identify BCAT1 as a potential therapeutic target for the clinical treatment of lung diseases and reveal a novel posttranscriptional regulatory mechanism and signaling pathway in hypoxia-induced PASMC autophagy." (PMID 32938905, 2020). "Moreover, high DNA methylation of the gene coding for branched chain amino acid transaminase 1 (BCAT1) in plasma may distinguish between lung disease and healthy individuals." (PMID 36497462, 2022).
lymph node metastasis (2 papers, 2021 to 2024). "BCAT1 expression was higher in patients with lymph node metastasis." (PMID 39324007, 2024).
ovarian tumors (2 papers, 2017 to 2025). "Finally, BCAT1 (branched chain amino-acid transaminase 1) is reportedly over-expressed in ovarian tumors, possibly through a mechanism involving hypomethylation." (PMID 28931403, 2017).
sarcoma (2 papers, 2015 to 2022). A usually aggressive malignant neoplasm of the soft tissue or bone. "BCAT1 expression was positively related to MSI in COAD, OV, and sarcoma (SARC), while it was negatively related to CHOL, prostate adenocarcinoma, and UCEC." (PMID 34984849, 2022). "However, in our screen, silencing of PSAT1, PHGDH or BCAT1 did not inhibit sarcoma cell growth, suggesting that these biosynthetic pathways may be of lesser importance for the sarcomatous malignancies studied here." (PMID 26499495, 2015).
teratocarcinoma (2 papers, 2012 to 2013). A germ cell tumor characterized by the presence of an embryonal carcinoma component and a teratoma component. "The mouse homologue of BCAT1 has been shown to be amplified and overexpressed in a teratocarcinoma cell line." (PMID 23758864, 2013). "Among these significant candidate genes, the mouse Bcat1 gene has shown to be amplified and over-expressed in a teratocarcinoma cell line." (PMID 22952821, 2012).
thyroid cancer (2 papers, 2016 to 2022). "Among these cancers, to the best of our knowledge, our study is the first to shed light on the diverse expression of BCAT1 in CHOL, kidney chromophobe, STAD, and thyroid carcinoma, suggesting the novelty of our research." (PMID 34984849, 2022).
asthma (1 paper, 2023). "BCAT1 is upregulated in mice with neonatal asthma, and BCAT1 inhibitors may inhibit airway inflammation and remodeling by reducing autophagy, which may provide a new therapeutic direction for childhood asthma." (PMID 38028625, 2023). "BCAT1 inhibitors alleviate childhood asthma in mice by affecting airway remodeling and autophagy." (PMID 38028625, 2023). "BCAT1 is upregulated in chronic airway disease; however, its role in childhood asthma is unclear." (PMID 38028625, 2023).
breast tumour (1 paper, 2024). "BCAT1 promotes cell proliferation by controlling the expression of the cell cycle inhibitor p27Kip1 and is required for hormone-independent breast tumour proliferation; silencing of BCAT1 leads to a massive reduction in tumour volume in an orthotopic triple-negative xenograft model." (PMID 38369471, 2024).
chronic lymphocytic leukemia (1 paper, 2025). "BCAT1-driven catabolism has been linked to enhanced growth: for instance, chronic lymphocytic leukemia cells are “avid consumers” of BCAAs, using BCAT1 bidirectionally to both degrade BCAAs and regenerate them as needed." (PMID 41502503, 2025).
chronic nasopharyngitis (1 paper, 2013). "The mRNA expression of c-Myc and BCAT1 was detected by RT-PCR in 6 chronic nasopharyngitis (CN) samples and 28 NPC samples." (PMID 23758864, 2013).
colon adenocarcinoma (1 paper, 2022). "For BCAT1, the most common mutation in cancers was missense mutation, and not less than 2.5% of patients with colon adenocarcinoma (COAD) and rectum adenocarcinoma (READ) had observed mutations." (PMID 34984849, 2022).
colorectal adenocarcinoma (1 paper, 2013). The most common type of colorectal carcinoma. "Consistent with our data, high BCAT1 expression is associated with a high incidence of metastasis resulting in an adverse disease-free survival in colorectal adenocarcinomas." (PMID 23758864, 2013).
crescentic glomerulonephritis (1 paper, 2025). A histopathologic term for a pattern of diseases characterized by extensive crescent formation in the glomeruli; patients present clinically with rapid deterioration of renal function, and possible progression to end-stage renal failure within weeks or months. "Inhibition of BCAT1 reduced glomerular crescents, serum creatinine, and proteinuria levels by suppressing macrophage infiltration in crescentic glomerulonephritis rats." (PMID 40546823, 2025).
dementia (1 paper, 2022). Loss of intellectual abilities interfering with an individual's social and occupational functions. "Furthermore, isoleucine is a metabolite linked to genes involved in neurological disorders, such as dementia and seizures: BCAT1, BCAT2, and IARS2 (26980008 and 30098844)." (PMID 35629950, 2022).
diabetes mellitus (1 paper, 2026). A metabolic disorder characterized by abnormally high blood sugar levels due to diminished production of insulin or insulin resistance/desensitization. "Compared with the normal control (NC) group, the BCAT2 protein level was significantly increased in the diabetes mellitus (DM) group, but the BCAT1 protein level had no significant change." (PMID 41503231, 2026).
diabetic retinopathy (1 paper, 2023). "Gabapentin, a leucine analog and specific inhibitor of BCAT1, reduced BCAA and MDA levels to ameliorate the decrease of GSH and increase of MDA in diabetic retinopathy." (PMID 37752100, 2023).
fibrosis (1 paper, 2018). the formation of excess fibrous connective tissue in an organ or tissue in a reparative or reactive process. "After controlling for age, BMI, fibrosis stage, and DM, the two BCAT1 gene probes (226517_at, 225285_at) were significantly upregulated with several histologic markers of advanced disease, including higher fibrosis stage, higher NAFLD activity scores, steatosis, lobular inflammation and ballooning." (PMID 30265706, 2018).
gastric tumors (1 paper, 2020). "Upregulation of BCAT1 was associated with poor prognosis in numerous types of tumors and its high expression significantly worsen overall survival in gastric tumors." (PMID 33363566, 2020).
glomerulonephritis (1 paper, 2017). A renal disorder characterized by damage in the glomeruli. "In a previous genome-wide expression quantitative trait loci analysis using inbred rat models of glomerulonephritis, we identified Bcat1 as the hub of a co-expression network in macrophages, suggesting its potential regulatory metabolic role in inflammatory disease." (PMID 28699638, 2017).
isovaleric acidemia (1 paper, 2022). "Because acetyl‐carnitine was increased in ivd‐1(tm6784); bcat‐1(hh58) and has been reported as a marker of adequate carnitine supplementation in the clinical treatment of isovaleric acidemia, we wondered whether increased isovaleric acid underline lower UPS functionality in ivd‐1(tm6784) mutants." (PMID 36168305, 2022).
lung squamous cell carcinoma (1 paper, 2022). "In contrast, low BCAT1 expression was observed in lung squamous cell carcinoma (LUSC)." (PMID 34984849, 2022).
medulloblastoma (1 paper, 2013). A malignant, invasive embryonal neoplasm arising from the cerebellum. "Retroviral transduction of BCAT1 into fetal rat brain cells with SV40 large T-antigen induced tumor formation with characteristic features of medulloblastoma." (PMID 23758864, 2013). "Both mRNA and protein levels of BCAT1 are higher in medulloblastoma patients with metastasis compared with those without metastasis (P < 0.01)." (PMID 23758864, 2013).
mesothelioma (1 paper, 2022). A usually malignant and aggressive neoplasm of the mesothelium which is often associated with exposure to asbestos. "There was a similar association between BCAT1 expression and PFIT for patients with ACC, BRCA, KIRC, LGG, mesothelioma, PAAD, and UVM." (PMID 34984849, 2022). "Moreover, the relevance between high BCAT1 expression and shorter DFIT can be observed in ACC and PAAD, while the upregulated expression of BCAT1 was relevant to poor PFIT for patients with ACC, BRCA, KIRC, LGG, mesothelioma, PAAD, and UVM." (PMID 34984849, 2022).
methylmalonic acidemia (1 paper, 2022). A genetically heterogenous inherited disorder characterized by abnormalities in the metabolism of lipids and proteins. "Theoretically, the inhibition of the upstream enzymes that are required to produce the toxic metabolite, such as inhibition of BCAT1 in methylmalonic acidemia, would provide an alternative method that is more feasible than preventing the intake of specific amino acids from the diet." (PMID 35736461, 2022).
muscle atrophy (1 paper, 2022). The loss of muscle tissue due to inactivity or disease. "Accordingly, further experiments are needed to confirm whether BCAT1 is also involved in the development of muscle atrophy in vivo, and whether changes in BCAT1 levels are associated with the progression of muscle atrophy." (PMID 35562710, 2022). "Although BCAT1 is expressed in skeletal muscle and plays an important role in muscle energy metabolism, the molecular basis of its involvement in the pathogenesis of muscle atrophy is still unclear." (PMID 35562710, 2022).
muscular atrophy (1 paper, 2022). "Therefore, we established a link between BCAT1 and muscular atrophy/sarcopenia." (PMID 35562710, 2022).
myelofibrosis (1 paper, 2020). A partial or complete replacement of the bone marrow stroma by fibrous tissue. "The loss of EZH2 led to the loss of repressive methylation of the BCAT1 promoter, leading to enhanced BCAT1 expression, sustained BCAA levels, progression of MPN (e.g., enhanced myelofibrosis) and transformation to AML." (PMID 33329600, 2020).
myeloproliferative neoplasm (1 paper, 2021). A clonal hematopoietic stem cell disorder, characterized by proliferation in the bone marrow of one or more of the myeloid (i.e., granulocytic, erythroid, megakaryocytic, and mast cell) lineages. "In NRASG12D-mutant myeloproliferative neoplasms, EZH2 deficiency is associated with elevated expression of BCAT1." (PMID 34109280, 2021).
myocardial ischemia (1 paper, 2022). A disorder of cardiac function caused by insufficient blood flow to the muscle tissue of the heart. "The BCAT1 and BCAT2 proteins highly ranking in KEGG results might play an important role in the regulation of metabolic pathway by RUS to improve myocardial ischemia." (PMID 35326233, 2022).
rectal cancer (1 paper, 2022). A primary or metastatic malignant neoplasm that affects the rectum. "This quantitative ctDNA test measuring levels of methylated BCAT1/IKZF1 DNA in blood reflects tumor burden at diagnosis and provides a baseline for demonstrating response to differing therapeutic approaches for colon and rectal cancer." (PMID 35000264, 2022).
renal carcinoma (1 paper, 2024). A carcinoma arising from the epithelium of the renal parenchyma or the renal pelvis. "However, the role and mechanism of BCAT1 in renal cancer is not clear." (PMID 39324007, 2024).
sarcopenia (1 paper, 2022). Progressive decline in muscle mass due to aging which results in decreased functional capacity of muscles. "Bcat1 expression level in skeletal muscles was lower in murine and cellular models of sarcopenia than in the control groups." (PMID 35562710, 2022). "Although skeletal muscle represents the most important site for BCAA transamination, the role of BCAT1 in human sarcopenia remains unknown." (PMID 35562710, 2022).
seminoma (1 paper, 2015). A radiosensitive malignant germ cell tumor found in the testis (especially undescended), and extragonadal sites (anterior mediastinum and pineal gland). "Furthermore, additional EC and pluripotency genes were upregulated (SOX2, LEFTY1 /2, DNMT3L, SALL4, DPPA5, BCAT1, FZD7, LIN28, ZIC3), while seminoma-associated genes where downregulated (SOX17, TFAP2C, cKIT, PRAME), without changing 5mC-levels." (PMID 26226633, 2015). "Among them, GDF3, NODAL, LEFTY1 /2, GAL, DPPA3, SOX2, DNMT3B /L, DPPA5, BCAT1, FGF2, PRDM14, ZIC3 and FZD7, while seminoma markers SOX17, cKIT and PRAME were downregulated." (PMID 26226633, 2015).
Sepsis (1 paper, 2024). Sepsis is defined as life-threatening organ dysfunction caused by a dysregulated host response to infection. "The potential role of BCAT1 in sepsis is also suggested by studies showing that elevated blood BCAA improves the catabolic effect of LPS on skeletal muscle protein synthesis in a mouse model of sepsis, which may provide a survival advantage in response to bacterial infection." (PMID 39262873, 2024). "The Venn diagram shows that a total of eight overlapping genes were discovered between ACSL4 co-expression genes and sepsis, including GK, CLEC4E, ACSL1, TGFBR3, ADAM9, AZI2, BCAT1, and CYP1B1." (PMID 39262873, 2024).
skin cutaneous melanoma (1 paper, 2022). "BCAT1 expression was significantly and positively associated with TMB in four cancers, including COAD, brain lower grade glioma (LGG), SARC, and skin cutaneous melanoma (SKCM)." (PMID 34984849, 2022).
steatosis (1 paper, 2018). Increased lipid within the cytoplasm of cells. "In a small cohort of patients with biopsy proven NAFLD, increased hepatic BCAT1 expression correlated with percentage of steatosis." (PMID 30265706, 2018).
T-cell lymphoma (1 paper, 2024). "First, we validated the interaction of BCAT1 with the KU70 and KU80 proteins using co-immunoprecipitation (Co-IP) in two human cell lines, the T-cell lymphoma CUTTL1 and embryonic kidney HEK 293T, expressing tagged BCAT1." (PMID 39769333, 2024).
thymoma (1 paper, 2022). A neoplasm arising from the epithelial cells of the thymus. "In our study, slight correlations between BCAT1 expression and neoantigen count were detected in thymoma and UCEC." (PMID 34984849, 2022).
uveal melanoma (1 paper, 2022). A melanoma derived from melanocytes of the uveal tract. "Through univariate Cox analysis, BCAT1 expression showed the risk factor of prognostic significance in eight cancers, containing adrenocortical carcinoma (ACC), BLCA, BRCA, KIRC, LGG, LIHC, PAAD, and uveal melanoma (UVM)." (PMID 34984849, 2022).
tumor (122 papers, 2007 to 2026). "High BCAT1 levels are associated with tumor proliferation and invasion, partly through activation of PI3K/Akt/mTOR and Wnt/β-catenin signaling cascades." (PMID 41502503, 2025). "Previous study has confirmed that overexpression of BCAT1 in CRC is associated with tumor progression and poor prognosis." (PMID 40313460, 2025). "In terms of KEGG pathways, overexpressed BCAT1 was positively associated with several tumor-related and angiogenesis-related pathways, such as JAK/STAT signaling pathway, mTOR signaling pathway, VEGF signaling pathway, and TOLL like receptor pathway." (PMID 38309289, 2024). "Increased BCAT1 expression has been associated with unfavorable prognosis in several tumor types, including BC, and it has been suggested its potential as an immunotherapeutic cancer marker." (PMID 38971778, 2024). "BCAT1 played tumor-promoting role in ccRCC and was closely associated with immunosuppressive cells and checkpoints." (PMID 38309289, 2024). "And in terms of HALLMARK pathways, overexpressed BCAT1 was also positively associated with tumor-related and angiogenesis-related pathways, such as KRAS signaling pathway, PI3K/Akt/mTOR signaling pathway, and Angiogenesis pathway." (PMID 38309289, 2024). "BCAT1 expression was associated with mismatch repair gene expression, immune checkpoint inhibitors expression, microsatellite instability, and tumor mutational burden in some cancers, indicating its potential in immunotherapy." (PMID 34984849, 2022). "Several studies focus on the activity of BCAT1 in cancer, as alteration in the expression of this enzyme is differentiated among the cancer types and is associated with tumor aggressiveness." (PMID 35409380, 2022). "PAK1 was previously reported to regulate cancer cell metabolism and proliferation and BCAT1 is implicated in cancer metabolic reprogramming, tumour metastasis and drug resistance." (PMID 35811334, 2022). "The association of BCAT1 gene expression with that of ERα and tumour progression has been explored in cell culture and murine models with only limited samples from patients with TNBC and non-specific IHC staining." (PMID 32571264, 2020). "By modelling the stage of neoplasia relative to marker mass, we show the potential for using the measured percentage of methylated BCAT1 and IKZF1 DNA in blood to estimate the relative risk of disease severity." (PMID 26445409, 2015). "Since BCAT1 is implicated in supporting cancer stem cells and survival under stress, an inhibitor might keep disseminated tumor cells in check or make adjuvant therapies more effective." (PMID 41502503, 2025). "Overexpression of BCAT1 has been associated with tumor aggressiveness and poor prognosis in NSCLC." (PMID 40469185, 2025). "Similarly, subcutaneous transplantation of BCAT1-deficient non-small lung cancer (NSCLC) cells into mice resulted in impaired xenograft tumour formation." (PMID 38369471, 2024). "Taken together, these data suggest that mutations in BCAT1 may have an impact on tumor progression and thus patient prognosis." (PMID 39324007, 2024). "Loss of BCAA catabolism with upregulated BCAT1 expression in tumours confers functional advantages, which could be exploited by therapeutic interventions to metabolic reprogramming for more ICC cases beyond genomic diversity." (PMID 37076565, 2023). "BCAT1 is an enzyme that converts branched-chain amino acids into the corresponding branched-chain α-keto acids and generates glutamate, and was reported to be associated with tumor growth and progression." (PMID 35569917, 2022). "In addition, BCAT1 induces ROS scavengers and attenuates ROS accumulation, and its expression in tumour cells is associated with enhanced proliferation and decreased apoptosis." (PMID 35842904, 2022). "Mounting evidence has linked overexpression of BCAT1 to tumor proliferation and progression." (PMID 34646394, 2021).